CDKN2A (cyclin dependent kinase inhibitor 2A)
Diseases named in the same sentence as CDKN2A in open-access papers (continued):
Sharing a sentence is not in itself a finding about the gene and the disease.
astrocytomas (continued). "Similarly to meningiomas, CDKN2A HD is a molecular signature for highest grade in IDH-mutant astrocytomas (grade 4) and in IDH-mutant and 1p/19q-codeleted oligodendroglioma (grade 3), regardless of histology." (PMID 37138345, 2023). "Furthermore, CDKN2A was completely inactivated in all the grade 4 IDHmut astrocytomas with PDGFRA amplification in TCGA and GLASS data with an exception of two cases (one in the GLASS and one in TCGA dataset), which carried only a PDGFRA amplification." (PMID 37932833, 2023). "Interestingly, the presence of homozygous deletions of CDKN2A/B directly impacts the prognosis, which association has also been established in the IDH mutant astrocytoma recently." (PMID 37537630, 2023). "CDKN2A/B HD have a direct oncogenic effect through loss of cell cycle inhibition and other parallel processes and are a molecular marker that influences grading and survival in IDH-mutant astrocytomas." (PMID 37504251, 2023). "This might be of relevance to assure sufficient tumor cell content for correct evaluation of deletions, e.g. the distinction of homozygous from hemizygous CDKN2A deletion in an IDH-mutant astrocytoma." (PMID 35361262, 2022). "For IDH mutant astrocytomas, any combination of microvascular proliferation, necrosis (characteristics of anaplastic astrocytomas) or CDKN2A/B homozygous deletion now allows for the diagnosis of Astrocytoma, IDH-mutant, WHO grade 4—note the use of Arabic is now suggested, rather than Roman, numbers." (PMID 33673104, 2021). "When IDH-mutated astrocytomas and oligodendrogliomas without known CDKN2A/B homozygous deletion were analyzed together (n=157), age did not significantly affect the hazard ratio for overall survival in univariable analysis (p=0.12)." (PMID 35083156, 2021). "Moreover, CDKN2A/B is one of the criteria to diagnose High-grade astrocytoma with piloid features alongside a piloid cytology, frequent MAPK pathway gene alterations, loss of ATRX nuclear expression, and a distinct DNA methylation pattern." (PMID 34638714, 2021). "Among the CDKN2A/B deleted tumors, all but two were astrocytomas grade 3." (PMID 35083156, 2021). "For TERTp mutation, EGFR highcopy amplification and CDKN2A homozygous deletion (recommended as upcoming diagnostic markers in the cIMPACT now update 3 and in a novel grading system for IDH-mutant astrocytomas) clinical sensitivity and specificity was equally 100%." (PMID 32758285, 2020). "Given the likelihood that CDKN2A status may be incorporated into future grading systems for IDHm astrocytomas, we sought to understand how such a change might impact the practice of neuropathology at our institution." (PMID 33081848, 2020). "Indeed, IDH-wildtype astrocytomas often harbor homozygous deletions in CDKN2A/B and are known to have a highly active microenvironment." (PMID 29616301, 2018). "Amongst grade 2/3 IDH1/2-mutant astrocytomas in the non-TCGA cohort with available survival data, 8.9% of cases (20 of the 224) had a hemizygous loss of CDKN2A/B while 15.6% (19 of the 122) of grade 4 cases had a hemizygous loss of CDKN2A/B." (PMID 39584448, 2025). "Given the prognostic role of both CDKN2A/B loss and focal amplifications, we sought to determine whether these two molecular markers could be integrated to refine the histopathologic stratification of IDH1/2-mutant astrocytoma." (PMID 39584448, 2025).
astrocytomas (continued). "The TCGA LGG dataset did not include information about CDKN2A/B and might be at risk of contamination regarding the presence of astrocytoma, WHO grade 4 cases based on WHO 2021 criteria." (PMID 38995493, 2024). "However, its ability to detect functional inactivation of CDKN2A/B through nonsynonymous CDKN2A/B mutation, which have recently been encountered in 2.6% of IDH-mut astrocytoma cases, or of heterozygous deletions might be reduced." (PMID 39593128, 2024). "Additionally, there is no apparent prognostic relevance for histologic grade in IDH-mutant astrocytoma with CDKN2A mutation/deletion unlike in those with wildtype CDKN2A." (PMID 39457569, 2024). "Combined WHO classification and proteomic subtyping, we clearly demonstrated that WHO_Grade4_IDH-mutant_astrocytomas featured with CDKN2A/B homozygous deletion could be grouped into S-Pf proteomic subtype, supported by their enhanced cell proliferation ability at protein level." (PMID 36720864, 2023). "Therefore, which regimen should be used in IDH-mutant astrocytomas with CDKN2A/B HD is debatable." (PMID 37504251, 2023). "In addition to histological Grade 4 IDH‐mutant astrocytoma, astrocytoma with IDH‐mutations of WHO Grades 2, 3 and homozygous CDKN2A and/or CDKN2B deletions are also defined as astrocytoma, IDH‐mutant, Grade 4, despite their relatively lower histopathology grades." (PMID 37667984, 2023). "Hence, CDKN2A homozygous deletion is now considered a CNS WHO grade 4 diagnostic marker in IDH-mutant astrocytomas, even in the absence of necrosis and/or microvascular proliferation on histology." (PMID 37138345, 2023). "Again, as these alterations do not result in the loss of genes neighbouring CDKN2A/B, this may also indicate the importance of these bystander genes in outcomes for astrocytomas with CDKN2A/B deletions." (PMID 37504251, 2023). "Based on recently published recommendations by the cIMPACT-NOW working group, CDKN2A status is likely to be incorporated into future grading systems for IDHm astrocytomas, but it remains unclear how to interpret the results of a commonly used testing modality, FISH, for this purpose." (PMID 33081848, 2020). "Additionally, the most frequent molecular abnormalities presented in astrocytomas (LOH 10p and LOH 10q; TP 53 mutations; EGFR amplification/chromosome 7 polysomy; EGFRvIII variant; CDKN2A deletions; IDH1 mutations) were used as markers of neoplastic cells at the DNA level." (PMID 25788865, 2014). "We report the case of a 31-year-old pregnant woman diagnosed at 24 + 5 weeks of gestation with an IDH1-mutant astrocytoma, WHO Grade 4, harboring a heterozygous CDKN2A/B deletion." (PMID 42294286, 2026). "Larger data are also need to determine if CDKN2A hemizygous deletion apparition might not be the first indicator of a genomic instability which evolves towards homozygosity as it has been suggested in the progression of IDH mutated astrocytomas." (PMID 40315229, 2025). "Compared to astrocytomas, GBM demonstrated a significantly decreased proportion of CDKN2A+ tumor cells, indicating an increased proportion of proliferating cells in GBM." (PMID 40264576, 2025). "Both CDKN2A homozygous and hemizygous deletions are enriched in post-treatment, recurrent IDH mutant astrocytomas." (PMID 40949165, 2025). "Alterations of CDK6, CDKN2A, CDKN2B, FGFR2, and MYC were more likely to be detected in WHO grade 4 astrocytoma, while variations of chromosome 19q had a higher frequency in WHO grade 2–3 astrocytoma." (PMID 38970209, 2024).
astrocytomas (continued). "Due to the presence of CDKN2A HD, the CNS WHO grade of 10 (11.3%) IDH-mutant astrocytomas was upgraded to grade 4 (2 were previously grade II, 8 were previously grade III according to the WHO 2016 at the time of diagnosis)." (PMID 38109891, 2024). "After the evaluation of CDKN2A status, the WHO CNS grade of 10 cases (2 grade II cases, 8 grade III cases) that harbored CDKN2A HD were changed to WHO CNS grade 4 IDH-mutant astrocytoma in accordance with WHO CNS 2021." (PMID 38109891, 2024). "Astrocytoma with IDH‐mutant and microvascular proliferation and/or necrosis and/or CDKN2A/B homozygous deletion was classified as WHO grade 4." (PMID 38970209, 2024). "This was a retrospective study involving a small number of patients with astrocytoma, IDH-mutant with CDKN2A-HD." (PMID 39117984, 2024). "In our study, 19% of astrocytoma, IDH-mutant showed CDKN2A-HD, which was consistent with the previous studies." (PMID 39117984, 2024). "If 1p/19q and CDKN2A/B are retained and the tumor lacks necrosis and/or microvascular proliferation (MVP), the classification is a grade 2 or 3 astrocytoma." (PMID 38203783, 2024). "Grading of mutant IDH astrocytomas retaining the CDKN2A/B gene relies on histological analysis to be differentiated into grade 2 and 3 mutant IDH astrocytomas." (PMID 39596840, 2024). "Genomic alterations of CDKN2A and CDKN2B in astrocytomas have been an evolving area of study for decades." (PMID 37504251, 2023). "Currently, molecular markers for clinical classification, prognosis, and therapeutic response prediction of astrocytoma include MGMT promoter methylation and homozygous CDKN2A and/or CDKN2B deletions." (PMID 37667984, 2023). "In IDH1-mutant astrocytoma cases with available clinical and CNA data (total 161 cases), we found that tumors harboring either CDKN2A deletion, PDGFRA amplification, CDK4 amplification, or MDM2 amplification conferred poor prognosis in these cohorts." (PMID 38012788, 2023). "The prognostic impact of CDKN2A homozygous deletion is crucial, especially in IDH-mutant astrocytomas." (PMID 36900302, 2023). "An astrocytoma, IDH mutant with WHO grade 4 is characterized by the presence of homozygous deletions of the tumor suppressor genes for CDKN2A or CDKN2B and/or microvascular proliferation and/or the presence of tumor necrosis." (PMID 36941392, 2023). "It is suspected that homozygous deletion of CDKN2A/B, which breaks the “brake” of tumor progression brake, nullifies the tumor‐suppressive environment created by IDH‐mutant astrocytomas." (PMID 37667984, 2023). "We acknowledge the relatively small size of our cohort, in particular tumours with CDKN2A/B homozygous deletion, related to IDH-mutant astrocytomas comprising a minority of all brain gliomas." (PMID 37316586, 2023). "As expected, recurrent homozygous deletions in CDKN2A and RB1 were present in TCGA diffuse gliomas and GLASS progressed grade 4 IDHmut astrocytomas." (PMID 37932833, 2023). "The gene set includes IDH1, IDH2, BRAF, CDKN2A/B, PTEN, and NOTCH1, but misses CIC, FUBP1, ATRX, and H3-3A important for oligodendroglioma and astrocytoma diagnosis." (PMID 37908227, 2023). "IDH-mutant astrocytomas are WHO grade 4 in the presence of microvascular proliferation, necrosis, and/or homozygous CDKN2A deletion, although other molecular features have been suggested as well." (PMID 35978439, 2022).
astrocytomas (continued). "This recommendation was based on multiple clinical studies indicating that CDKN2A/B homozygous deletion is a strong adverse prognostic factor, as this genetic alteration renders IDH-mutant astrocytoma ~50% (61 v." (PMID 35203456, 2022). "In other words, the presence of homozygous CDKN2A/B deletion is a marker of the highest malignancy grade in the group of diffuse, IDH-mutant astrocytomas." (PMID 34638714, 2021). "Based on the robust literature and the cIMPACT-NOW update 5 recommendations, astrocytoma, IDH-mutant that harbors homozygous CDKN2A/B deletion is graded as CNS WHO grade 4." (PMID 34638714, 2021). "that used FISH to examine CDKN2A, CDK4, and PDGFRA copy number alterations in grade 2 and 3 astrocytomas." (PMID 33081848, 2020). "We began by constructing K-M survival curves of primary IDHm astrocytomas, stratified both by WHO histologic grade and CDKN2A deletion." (PMID 33081848, 2020). "To address this issue, we performed a retrospective analysis of prospectively collected CDKN2A FISH data from 108 primary and 43 recurrent IDH-mutant astrocytomas diagnosed between 2007–2020 at the University of Pittsburgh Medical Center." (PMID 33081848, 2020). "Now, many other genes such as LHX9, MGMT, CDKN2A, PTEN, and P15 have been shown to be methylated in astrocytomas." (PMID 20334650, 2010). "In addition, 3 samples with astrocytoma, IDH-mutant (WHO grade II: 1; WHO grade III: 2) were graded as CNS WHO grade 4 as they harbored homozygous deletions of CDKN2A/B (all LTS)." (PMID 39954095, 2025). "Focal amplifications were also prognostically informative in IDH1/2-mutant astrocytomas with intact CDKN2A/B within the non-TCGA cohort." (PMID 39584448, 2025). "In non-TCGA IDH1/2-mutant astrocytomas, CCND2 alteration (HR: 3.05), EGFR amplification (HR: 2.43), CDKN2A/B loss (homozygous or heterozygous loss, HR: 2.28), 22q loss (HR: 1.97), and PDGFRA alteration (HR: 1.92) were negatively prognostic." (PMID 39164213, 2025). "The prognostic negative impact of CDKN2A/B deletion in IDHm astrocytomas with morphological lower-grade features is established and the reason for the molecular criteria of WHO grade 4 astrocytomas." (PMID 40392514, 2025). "For instance, earlier studies have not systematically accounted for the double impact of a CDKN2A/B deletion in tumors with morphologically defined WHO grade 4 astrocytomas." (PMID 40392514, 2025). "Several studies have explored the prognostic value of mitotic activity by assessing consecutive high-power fields, revealing worse outcomes for IDH-mutant astrocytomas in the absence of CDKN2A/B HD." (PMID 39382765, 2024). "Additionally, astrocytoma with IDH-mutant grade III and synonymous CDKN2B and/or CDKN2A deletions were also characterized as astrocytoma, IDH mutations, grade IV, albeit with a relatively low histopathologic grade." (PMID 38919539, 2024). "In the “cIMPACT-NOW” published in 2020, it was recommended that astrocytomas containing CDKN2A/B HD be considered WHO grade IV (2016) astrocytomas even if there is no microvascular proliferation (MVP) or necrosis." (PMID 38109891, 2024). "Further molecular characterization of the mutant IDH astrocytoma includes detection of the presence or absence of the CDKN2A/B gene." (PMID 39596840, 2024). "A recent study suggested that EGFR Amp in WHO grade 4 IDH-mutant astrocytoma was not related to worse OS, unless CDKN2A/B homozygous deletion were also detected." (PMID 38595969, 2024). "In this study, we observed a correlation between presence of T2-FLAIR mismatch sign and CDKN2A-intact in non-enhancing astrocytoma, IDH-mutant." (PMID 39117984, 2024). "Almost all data could be separated between IDH-mut astrocytoma, IDH-wt GBM and IDH-mut 1p/19q codeleted ODG regarding their p16 IHC testing and CDKN2A/B status." (PMID 39593128, 2024). "Our study confirms the strong negative prognostic value of CDKN2A homozygous deletion in IDH-mutant astrocytoma patients." (PMID 38183430, 2024).
astrocytomas (continued). "Furthermore, we provide possible future avenues to improve histomolecular prognostic assessment of IDH-mutant astrocytoma based on CNS WHO grade, global DNA methylation level, and CDKN2A homozygous deletion." (PMID 38183430, 2024). "Our research corroborates the significant negative impact that homozygous deletion of CDKN2A has on the prognosis of patients with IDH-mut astrocytoma." (PMID 39593128, 2024). "Histological grading is challenging, and aside from CDKN2A/B homozygous deletions in IDH-mutant astrocytomas, there are no other objective molecular markers used for grading." (PMID 39382765, 2024). "CDKN2A/B homozygous deletions were previously identified as a negative prognostic factor in IDH-mutant astrocytomas in update 5 of the Consortium to Inform Molecular and Practical Approaches to CNS Tumor Taxonomy." (PMID 39457569, 2024). "The T2-FLAIR mismatch sign is one of the potential predictors of CDKN2A status in patients with non-enhancing astrocytoma, IDH-mutant." (PMID 39117984, 2024). "However, patients with astrocytoma, IDH-mutant with CDKN2A/B-HD have shorter survival (expected median OS: approximately 3 years) which corresponds to WHO CNS grade 4." (PMID 39117984, 2024). "They suggested that IDH-mutant astrocytomas with CDKN2A HD should be considered grade 4 tumours irrespective of the presence of microvascular proliferation or necrosis." (PMID 37504251, 2023). "CDKN2A/B HD has been demonstrated to be strongly associated with poor prognosis in IDH-mutant astrocytomas, and the WHO CNS5 defines IDH-mutant astrocytomas with CDKN2A/B HD as CNS WHO grade 4, regardless of histological findings." (PMID 38012788, 2023). "As such, IDH-mutant astrocytomas with CDKN2A/B HD are classified as grade 4 tumours independent of morphologic features." (PMID 37504251, 2023). "It is unclear why this report differs from the majority of other studies, but it highlights that not all studies support the role of CDKN2A/B HD as a prognostic marker in IDH-mutant astrocytomas." (PMID 37504251, 2023). "It should be noted that CDKN2A/B homozygous deletions is a strong indicator for poor prognosis and has been distinguished from Glioblastoma to be categorized as IDH-mutant astrocytoma: astrocytoma, IDH-mutant, CNS WHO grade IV." (PMID 37275361, 2023). "The latest CNS tumor classification has indicated that CDKN2A/B homozygous deletion represents a poor prognosis in astrocytoma, but there are no reports using CDKN2A/B and MRI features to predict survival in LGGs." (PMID 37190513, 2023). "Overall, the evidence supports the use of CDKN2A/B HD as a negative prognostic marker in IDH-mutant astrocytomas." (PMID 37504251, 2023). "There is no clear consensus on the treatment of IDH-mutant astrocytomas with CDKN2A/B HD, and reports related to their management are scarce." (PMID 37504251, 2023). "The grading of IDH-mutant astrocytomas also relies on a combination of histomorphological, as well as molecular traits: the presence of CDKN2A/B homozygous deletion and/or necrosis and/or microvascular proliferation defines a CNS WHO grade 4 lesion in IDH-mutant astrocytomas." (PMID 38106649, 2023). "In addition to CDKN2A HD, recent studies indicated that CDKN2A hemizygous deletion also confers worse prognosis in IDH-mutant astrocytoma." (PMID 38012788, 2023). "The presence of the homozygous deletion of the CDKN2A gene defines a group of patients with a worse prognosis, and it allows alone the classification of a tumor as “astrocytoma, grade 4” regardless of the histological features." (PMID 35267432, 2022). "Heterozygous CDKN2A/B deletion has not been shown to have a definitive effect on grading of IDH-mutant astrocytomas, and has not been previously documented in the setting of a dual IDH1/2 mutation." (PMID 36286062, 2022).